RN7SKP64 (RN7SK pseudogene 64)
Gene: Miscellaneous RNA gene on chromosome 5 (139,333,038 to 139,333,365, reverse strand). Ensembl gene ENSG00000253015.
Homologues: Orthologues: chimpanzee 7SK (92% identical), mouse Gm56250 (51% identical), guinea pig 7SK (45% identical). Paralogues in human: RN7SKP180 (61% identical), RN7SKP1 (59% identical), RN7SKP255 (59% identical), RN7SKP176 (58% identical), RN7SKP269 (58% identical), RN7SKP204 (58% identical), RN7SKP137 (58% identical), RN7SKP20 (57% identical), RN7SKP243 (57% identical), RN7SKP9 (57% identical), RN7SKP139 (57% identical), RN7SKP146 (57% identical), and 283 more.